KCNS3 (potassium voltage-gated channel modifier subfamily S member 3)
Synonyms: Kv9.3
Tractability: Small molecule: an approved drug acts on it; it belongs to a druggable protein family. Antibody: UniProt places it where antibodies can reach, with high confidence; its Gene Ontology location is reachable by antibodies, with high confidence; UniProt predicts a signal peptide or a membrane-spanning region; the Human Protein Atlas places it where antibodies can reach.
Gene: Protein-coding gene on chromosome 2 (17,877,847 to 18,361,616, forward strand). Ensembl gene ENSG00000170745.
Subcellular location: Cell membrane
Subcellular location (Human Protein Atlas): Cytosol; Golgi apparatus; Plasma membrane
Pathways (Reactome):
Metabolism: Glucagon-like Peptide-1 (GLP1) regulates insulin secretion
Neuronal System: Voltage gated Potassium channels
Gene Ontology:
Molecular function: delayed rectifier potassium channel activity; potassium channel regulator activity; monoatomic ion channel activity; voltage-gated potassium channel activity
Biological process: action potential; potassium ion transmembrane transport; potassium ion transport; regulation of potassium ion transmembrane transport; monoatomic ion transport; protein homooligomerization; transmembrane transport
Cellular component: cytosol; plasma membrane; membrane; voltage-gated potassium channel complex; cytoplasm
Genetic constraint (gnomAD): Loss-of-function variants: 14 observed, 33.92 expected, observed/expected ratio (o/e) 0.41, 90% interval 0.27 to 0.64. The upper end of that interval is the gene's LOEUF score, 0.64, which puts it in group 2 of 6, group 1 being the genes least tolerant of losing a copy. Missense variants: 541 observed, 649.03 expected, observed/expected ratio (o/e) 0.83, 90% interval 0.78 to 0.89. Synonymous variants: 238 observed, 253.12 expected, observed/expected ratio (o/e) 0.94, 90% interval 0.85 to 1.05.
Homologues: Orthologues: chimpanzee KCNS3 (99% identical), macaque KCNS3 (99% identical), rabbit KCNS3 (97% identical), dog KCNS3 (97% identical), pig KCNS3 (96% identical), rat Kcns3 (96% identical), mouse Kcns3 (95% identical), guinea pig KCNS3 (91% identical), tropical clawed frog kcns3 (78% identical), zebrafish kcns3a (62% identical), zebrafish kcns3b (44% identical). Paralogues in human: KCNS2 (52% identical), KCNS1 (45% identical), KCNB2 (41% identical), KCNV1 (39% identical), KCNV2 (34% identical), KCNG1 (33% identical), KCNF1 (32% identical), KCNG4 (32% identical), KCNC3 (30% identical), KCNC2 (30% identical), KCNA4 (30% identical), and 19 more.
Diseases named in the same sentence as KCNS3 in open-access papers:
KCNS3 is named in the same sentence as 17 diseases in open-access papers, as found by Europe PMC text mining. Sharing a sentence is not in itself a finding about the gene and the disease. The quoted sentences say what the papers report.
schizophrenia (5 papers, 2012 to 2023). A major psychotic disorder characterized by abnormalities in the perception or expression of reality. "In addition, the lower Kcns3 levels provide a new molecular mechanism of neuron dysfunction in schizophrenia, which encodes potassium channel-associated subunits." (PMID 37670341, 2023). "Interestingly, lower expression of Kcns3 was found in PV-neurons in the PFC in schizophrenia patients." (PMID 35058780, 2021). "KCNS3 and LHX6 might be useful for characterizing cell-type specific molecular alterations of cortical GABA neurotransmission and for the development of novel treatments targeting PV and/or SST neurons in schizophrenia." (PMID 22937123, 2012).
lung adenocarcinoma (3 papers, 2015 to 2023). A carcinoma that arises from the lung and is characterized by the presence of malignant glandular epithelial cells. "The deletion of potassium voltage-gated channel modifier subfamily S member 3 (KCNS3 or Kv9.3) in lung adenocarcinoma (LUAD) cell lines inhibits cell proliferation by cell cycle arrest in the G0/G1 phase." (PMID 37408210, 2023). "Interestingly, the knockdown of KCNS3 inhibits tumor cell proliferation in colon carcinoma and lung adenocarcinoma cell lines." (PMID 37641095, 2023).
lung carcinoma (3 papers, 2015 to 2025). "Other genes were reported in the context of other cancer types, e.g. AHCYL2 as having a potential role in melanoma, colorectal, ovarian, and lung cancer, and KCNS3 as potentially relevant in colon and lung cancers." (PMID 39825380, 2025).
epilepsy (2 papers, 2015 to 2021). A brain disorder characterized by episodes of abnormally increased neuronal discharge resulting in transient episodes of sensory or motor neurological dysfunction, or psychic dysfunction. "Thus, the combined decreased expression of Kcna3 (Kv1.3), Kcnk9 (TASK3), Kcnn3 (SK3), Kcng3 (Kv7.3), and Kcns3 (Kv9.3) around day 8 could lead to increased chances of persistent membrane depolarization, which ultimately may lead to epilepsy." (PMID 34877936, 2021).
airway hyperresponsiveness (1 paper, 2013). "SNPs in KCNS3, which encodes a voltage-gated potassium channel protein, were associated with airway hyperresponsiveness in past studies, which is of interest given postulated associations of airways hyperresponsiveness with an accelerated rate of FEV1 decline and risk of COPD." (PMID 24274704, 2013).
asthma (1 paper, 2013). "Dexamethasone, which is a glucocorticoid used to treat both asthma and COPD, is associated with expression of both KCNS3 and FSTL1; interestingly, there are striking similarities in the effects of dexamethasone and 1,25-dihydroxyvitamin on the expression of these genes." (PMID 24274704, 2013).
esophageal squamous cell carcinoma (1 paper, 2024). Esophageal squamous cell carcinoma (ESCC) is a type of esophageal carcinoma (EC) that can affect any part of the esophagus, but is usually located in the upper or middle third. "KCNS3 has been identified as part of a prognostic signature separating high- and low-risk groups in esophageal squamous cell carcinoma (ESCC) patients." (PMID 38792020, 2024).
cancer (5 papers, 2015 to 2025). A tumor composed of atypical neoplastic, often pleomorphic cells that invade other tissues. "As for methylation, GNGT1, KCNS3, GCG and PPKACG tended to be hypomethylated in pan-cancer while ADCY8 tended to be hypermethylated." (PMID 39104385, 2024).
KCNS3 also shares sentences with these, for which no sentence is quoted: colon carcinoma (2 papers); tumor (2); uterine cancer (2); breast carcinoma (1); endotoxemia (1); hypoxia (1); melanoma (1); metabolic disease (1); pulmonary diseases (1).